COL4A4 (collagen type IV alpha 4 chain)
Diseases named in the same sentence as COL4A4 in open-access papers (continued):
Sharing a sentence is not in itself a finding about the gene and the disease.
renal failure (16 papers, 2012 to 2025). "This study confirms the wide phenotypic spectrum associated with mono-allelic COL4A3/COL4A4 variants, extending from isolated microscopic hematuria to kidney failure with high intra- and interfamilial variability." (PMID 36925663, 2023). "In conclusion, this study confirms that mono-allelic COL4A3 or COL4A4 variants are associated with a wide clinical and pathological spectrum of kidney disease, ranging from isolated microscopic hematuria to kidney failure." (PMID 36925663, 2023). "Two Romani siblings heterozygous for p.Gly533Asp COL4A4 variant had isolated proteinuria and progressed to renal failure at 18 and 61 years, respectively." (PMID 36844206, 2023). "Heterozygote carriers of frameshift/splicing variants in COL4A3/COL4A4 presented a higher risk of developing renal failure than those with missense variants in the glycine domains (p = 0.015)." (PMID 33369211, 2021). "Heterozygous carriers of frameshift/splicing variants in COL4A3/COL4A4 presented a higher risk of developing renal failure than those with missense variants in the glycine domains (p = 0.015)." (PMID 33369211, 2021). "Heterozygous variants in COL4A3 and COL4A4 were found in 14 families for a total of 34 patients: of them, 96% presented with microhematuria and 8 out 34 (24%) developed renal failure at a mean age of 65 years." (PMID 33369211, 2021). "Eight (24%) of the 34 heterozygous COL4A3 and COL4A4 carriers developed renal failure at a mean age of 57 years, with a significantly lower risk than hemizygous COL4A5 or double heterozygous COL4A3/COL4A4 carriers (p < 0.01), but not different from that of the heterozygous COL4A5 females (p = 0.6)." (PMID 33369211, 2021). "Nonsense COL4A3 and COL4A4 mutations were also associated with a younger age at renal failure." (PMID 27627812, 2016). "By incorporating genetic markers such as variants in COL4A3, COL4A4, and COL4A5, our study design can address the variable progression rates from diagnosis to renal failure." (PMID 40165927, 2025). "Renal failure is less common, but recognised increasingly, with pathogenic heterozygous COL4A3 or COL4A4 variants." (PMID 33854215, 2021). "The age at onset of renal failure was known for some homozygous or compound heterozygous COL4A3 (n = 35) and COL4A4 (n = 25) pathogenic mutations where both variants were known." (PMID 27627812, 2016). "The age at onset of renal failure was also the same for homozygous and for compound heterozygous COL4A3 and COL4A4 mutations (21.5 ± 7.2, 95%CI 17.2–25.9, n = 13; and 21.8 ± 7.0, 95% CI 19.8 to 23.7, n = 52)." (PMID 27627812, 2016). "Individuals with at least one direct nonsense COL4A3 or COL4A4 mutation also developed renal failure at a younger age than those with none." (PMID 27627812, 2016). "This study confirmed that two COL4A3 or COL4A4 mutations resulted in earlier onset renal failure than one or no severe mutations." (PMID 27627812, 2016). "For the COL4A3 and COL4A4 genes, age at renal failure occurred sooner with two non-missense variants (p = 0.08, and p = 0.01 respectively)." (PMID 27627812, 2016). "Alport disease in humans, which usually results in proteinuria and kidney failure, is caused by mutations to the COL4A3, COL4A4, or COL4A5 genes, and absence of collagen α3α4α5(IV) networks found in mature kidney glomerular basement membrane (GBM)." (PMID 23236390, 2012).
chronic kidney disease (15 papers, 2015 to 2026). Impairment of the renal function secondary to chronic kidney damage persisting for three or more months. "The rate of progression to end stage renal disease is much lower in patients harbouring a single pathogenic variant in the recessive COL4A4 gene when compared with those found to have bi-allelic COL4A4 pathogenic variants." (PMID 39127776, 2024). "Furthermore, in clinically affected patients with heterozygous variants in COL4A3, COL4A4 an increased risk of progression to chronic renal failure was observed in up to 38% and a progression to ESRD was observed in up to 20%." (PMID 29946535, 2018). "Historically, it was diagnosed only when significant chronic kidney disease developed; however, more recently, ADAS has been accepted as present when a pathogenic mutation is identified in a COL4A3 or COL4A4 gene." (PMID 41257164, 2025). "The same variant (COL4A4 c.594+1G>A; NM_000092.5) was also found in 64-year-old male (A494487) from a different, unrelated family, who at the time of diagnosis, had chronic kidney disease (CKD) stage IV and his kidney histology revealed FSGS." (PMID 35419377, 2022). "Since patients with heterozygous mutations of COL4A3 or COL4A4 have shown a wide spectrum of disease from TBMN to ADAS, a systematic review has been performed and shown that 29% developed chronic kidney disease (CKD) and 15.1% reached end-stage kidney disease (ESKD)." (PMID 36292665, 2022). "One person with heterozygous COL4A4 variant reached KF at the age 55, while eGFR (estimated glomerular filtration rate, using CKD-EPI, Chronic Kidney Disease Epidemiology Collaboration formula) <30 ml/min/1.73 m2 was revealed in 11% (2/18) of individuals with COL4A4 changes." (PMID 35419377, 2022). "As a disease of type IV collagen caused by variants in collagen IV genes (COL4A3, COL4A4, and COL4A5), AS weakens the structural integrity of basement membranes, and leads to chronic kidney disease (CKD), hearing loss, and eye abnormalities." (PMID 40485716, 2025). "COL4A4: collagen 4 alpha 4, COL4A5: collagen 4 alpha 5, ESRD: end-stage renal disease." (PMID 41257164, 2025).
glomerular disease (13 papers, 2013 to 2025). "Although a more precise assessment of the frequency of individuals with a pathogenic variant in COL4A3/COL4A4 is needed, these remain the most common pathogenic variants in genes associated with monogenic glomerular diseases." (PMID 40115110, 2025). "The genes with the highest lifetime risk for monogenic glomerulopathy were COL4A3, followed by COL4A4, CRB2, NPHS1, and NPHS2." (PMID 40677321, 2025). "Although FSGS is frequently considered a primary glomerular disease, it can also represent the histological manifestation of genetic disorders affecting the GBM, including mutations in COL4A3, COL4A4 or COL4A5 genes." (PMID 41562995, 2025). "In the proband, only a novel heterozygous variant, c.1856G>A (p.Gly619Asp) in the exon 25 of the COL4A4 gene, was suspected to be the pathogenic variant, and no other variants in the known disease‐causing genes for glomerular disorders were identified." (PMID 27469977, 2016).
microhematuria (13 papers, 2016 to 2025). "In our cohort, among 16 patients with COL4A3 or COL4A4 variants—including those with both genes affected—15 showed microscopic hematuria, all 16 developed proteinuria, and 13 had been noted to have microscopic hematuria during school urinalysis." (PMID 40753325, 2025). "In one of the largest studies of ADAS, a Spanish cohort involving 82 families and 252 patients with pathogenic COL4A3 or COL4A4 mutations, microscopic hematuria was the most common finding." (PMID 41257164, 2025). "The case at hand is familial microscopic hematuria due to heterozygous disease-causing variants in the COL4A3 or COL4A4 gene, or even the COL4A5 gene (in women), responsible for the X-linked form of AS." (PMID 37761826, 2023). "In a report of 53 patients with heterozygous COL4A3/COL4A4 mutations in 25 families, microhematuria, proteinuria (>0.2 g/g⋅Cr), CKD, and ESKD were observed in 100%, 17%, 7.5%, and 5.7% of subjects, respectively." (PMID 36292665, 2022). "Pathogenic/likely pathogenic (P/LP) sequence variants in the COL4A3/COL4A4 genes cause a condition that is under-recognized (ranging from completely normal urine sediment to microhematuria, proteinuria and renal insufficiency), poorly understood and not yet well classified." (PMID 38317457, 2024). "In this present study, the COL4A4 c1459 + G > A was first reported in the literature as a heterozygous change in a 35-year old female proband with history of microhematuria, mild proteinuria and uniformly thinned GBM (144–204 nm)." (PMID 26833262, 2016). "In a systematic review of 777 patients with heterozygous COL4A3/COL4A4 mutations in 258 families, 28.6% of whom received kidney biopsy; microhematuria with/without macrohematuria, proteinuria (>0.5 g/day), CKD, and ESKD were observed in 89.1%, 41.6%, 29%, and 15.1%, respectively." (PMID 36292665, 2022). "In pedigree 1, isolated microscopic hematuria, normal renal function, and absence of other signs related to AS in the proband, his mother, and grandfather, are more suggestive of a heterozygous COL4A4-related BFH than AS." (PMID 36699462, 2022).
hearing loss (10 papers, 2020 to 2025). "Heterozygotes with a pathogenic COL4A3 or COL4A4 variant have hematuria, and sometimes proteinuria, kidney impairment, and hypertension, but they rarely have sensorineural hearing impairment or ocular abnormalities." (PMID 40004525, 2025). "Among these elements, we identified six potential variants in cis-regulatory elements associated with hearing loss genes, CDH23, OTOF, MYO6, COL4A4 and WHRN." (PMID 40164689, 2025). "Several collagen genes (COL1A1, COL1A2, COL2A1, COL4A3, COL4A4, COL4A5, COL11A1, and COL11A2) are associated with hereditary syndromic hearing loss." (PMID 33848312, 2021). "The authors also argue that there is no unmistakable evidence that one mutation in COL4A3 or COL4A4 gene without disease modifying factors can be responsible for the characteristic ultrastructural signs of AS, hearing impairment, or eye abnormalities." (PMID 34212557, 2021).
benign familial hematuria (9 papers, 2015 to 2025). "In previous reports of COL4A3 and COL4A4 mutations, the terms "familial benign hematuria (BFH)" and "thin GBM disease" were used." (PMID 38978054, 2024). "COL4A5 mutations are associated with the major X-linked form of the disease, and COL4A3 and COL4A4 mutations are associated with autosomal recessive, dominant forms, and benign familial hematuria." (PMID 30293132, 2019).
Hematuria (8 papers, 2016 to 2025). The presence of blood in the urine. "The COL4A4 variant is significantly associated with both traits (p < 7.95E−35 for hematuria and p < 4.0E−77 for uACR as a quantitative measure) and the composite (p < 8.88E−31)." (PMID 37872228, 2023). "In this study, two variants in the COL4A4 gene were identified in two unrelated Chinese pedigrees with familial hematuria." (PMID 36699462, 2022). "Taken together, a novel c.595-1G>A variant and a known c.1715G>C (p.Gly572Ala) variant of the COL4A4 gene were identified in two Chinese families with familial hematuria, respectively." (PMID 36699462, 2022). "Identification of the COL4A4 gene variants in two pedigrees with familial hematuria." (PMID 36699462, 2022).
Hypertension (7 papers, 2021 to 2025). The presence of chronic increased pressure in the systemic arterial system. "It is caused by a mutation in the collagen type IV alpha-4 (COL4A4) gene, which produces type IV collagen, and often manifests in individuals with hematuria, proteinuria, edema, and hypertension." (PMID 39398663, 2024). "The finding that the gene collapsing analyses in essential hypertension identified variation in genes (PKD1, PKD2, COL4A4, UMOD, CACNA1D, and NR3C2) that are possible causes of undiagnosed secondary hypertension is worthy a special comment." (PMID 37059828, 2023). "A prior study indicated that people with seemingly benign hematuria and TBMD might carry heterozygous mutations in the COL4A3/COL4A4 genes, raising the risks of ESRD, hypertension and proteinuria." (PMID 39830308, 2025). "However, a variable proportion of COL4A3 or COL4A4 carriers progress to proteinuria, hypertension, and ESRD, which raises the question of the nomenclature of autosomal dominant AS (ADAS)." (PMID 34212557, 2021).
IgA nephropathy (6 papers, 2022 to 2024). "In this study, the pathological diagnosis of the proband’s sister (II-2) confirmed IgA nephropathy, and genetic testing suggested a mutation in the Col4A4 and TNXB gene." (PMID 37323683, 2023). "The IgA deposits within the mesangium corresponding to IgA nephropathy could be due to the predisposition of mesangial IgA deposition in defective GBMs caused by COL4A4 variant." (PMID 36699462, 2022). "It is unclear whether severe variants predispose more often to kidney cysts or coincidental IgA glomerulonephritis which are recognized increasingly in COL4A3-, COL4A4 - and COL4A5-associated disease." (PMID 35602506, 2022). "However, some variants in the COL4A3, COL4A4, or COL4A5 gene seem to increase the susceptibility to IgA nephropathy, which is supported by IgA deposits occasionally observed in the AS patients and the COL4A3, COL4A4, or COL4A5 gene variants reported in a minority of IgA nephropathy patients." (PMID 36699462, 2022). "We found that BMP2, COL4A3, and COL4A4 were not upregulated either in other glomerular cells in PMN or in podocytes/HRMCs in IgA nephropathy." (PMID 38785168, 2024). "An ARAS carrier of c.1598G>A, p.(Gly533Asp) in COL4A4, had been initially diagnosed with IgA nephropathy due to non-specific pathological findings in a renal biopsy performed due to hematuria and proteinuria." (PMID 39202375, 2024).
Kidney Cyst (6 papers, 2022 to 2025). Abnormal fluid filled sac within the kidney, either acquired or congenital. "This study clarified that kidney cysts are a more frequent occurrence in individuals with COL4A3 or COL4A4 variants than previously acknowledged and stressed the importance of considering AS in the differential diagnosis of hereditary cystic kidney diseases." (PMID 40565535, 2025). "They conducted a study on 157 adults with pathogenic or likely pathogenic variants in the COL4A3 or COL4A4 genes and found that 53.5% had at least one kidney cyst (1+ KC) in either kidney, and 28.0% had three or more kidney cysts (3+ KCs) in either kidney." (PMID 40565535, 2025). "A cystic phenotype is increasingly recognized in association with disorders caused by pathogenic variants in the COL4A3, COL4A4, and COL4A5 genes; several studies have investigated the prevalence of kidney cysts in individuals with these genetic variants." (PMID 40565535, 2025).
nephrotic syndrome (6 papers, 2005 to 2024). A collection of symptoms that include severe edema, proteinuria, and hypoalbuminemia; it is indicative of renal dysfunction. "The nail-patella syndrome results from dominant autosomal mutation in the transcription factor LMX1B, which regulates genes COL4A3 and COL4A4 and the children have nephrotic syndrome and skeletal and nail dysplasia." (PMID 16878253, 2005). "COL4A3, COL4A4 and COL4A5 genes should be included in steroid-resistant nephrotic syndrome genetic panels." (PMID 38780768, 2024). "Though COL4A4 is listed on commercial gene panels for nephrotic syndrome, the turnaround time is 4 weeks and results would not have returned prior to the planned biopsy." (PMID 35141181, 2021).
end stage renal disease (5 papers, 2015 to 2025). "The average age at end-stage renal failure was the same for all mutations in COL4A5 (24.4 ±7.8 years), COL4A3 (23.3 ± 9.3) and COL4A4 (25.4 ± 10.3) (COL4A5 and COL4A3, p = 0.45; COL4A5 and COL4A4, p = 0.55; COL4A3 and COL4A4, p = 0.41)." (PMID 27627812, 2016). "Age at end-stage renal failure and severity of mutations with COL4A5, COL4A3 and COL4A4 variants." (PMID 27627812, 2016). "Overall the mean age at onset of end-stage renal failure was not different for individuals with COL4A3 (23.2 + 9.3, years, 95% CI 20.1 to 26.5) or COL4A4 mutations (mean 25.4 ±10.3 years, 95% CI 21.3 to 29.6) compared with COL4A5 mutations (24.4 ± 7.8 years, 95% CI 23.4 to 25.4, n = 237)." (PMID 27627812, 2016). "However this study did not demonstrate any difference in the age at end-stage renal failure due to Gly substitutions with Arg, Glu or Asp compared with other substitutions for COL4A3 and COL4A4." (PMID 27627812, 2016).
cystic kidney disease (4 papers, 2019 to 2026). A congenital or acquired kidney disorder characterized by the presence of renal cysts. "In line with previous reports renal cysts were also observed in family 1 affected members who harbor the combination of LAMA5/COL4A4 mutations." (PMID 30808327, 2019). "While ADPKD is predominantly associated with PKD1 and PKD2 gene variants, there are documented cases where individuals with pathogenic variants in COL4A3, COL4A4, or COL4A5 also present with renal cysts and even a clinical diagnosis of polycystic kidney disease (PKD)." (PMID 40565535, 2025). "Furthermore, the available evidence indicates that renal cysts can indeed be a feature in individuals harboring variants in COL4A3, COL4A4, and COL4A5." (PMID 40565535, 2025). "Notably, COL4A3 and COL4A4 are specifically mentioned as genes to be included in cystic kidney disease panels." (PMID 40565535, 2025).
deafness (4 papers, 2018 to 2025). An inherited or acquired condition characterized by the complete loss of the ability to hear from one or both ears. "For example, there were three genes which appeared to be strongly and specifically expressed in pillar cells, Col4a4 and Col4a3, which are known deafness genes, and Thsd7a, which is a gene with high variant loads in female and all participants with self-reported hearing difficulty (cluster 2K)." (PMID 35761239, 2022). "In the Western Romanian population studied, the risk of deafness is given by pathogenic variants in 7 genes included in the panel: GJB2, USH2A, LOXHD1, SLC26A4, USH1C, COL4A4, COL4A3, present in almost 10% of the cohort, therefore representing a significant risk." (PMID 41303398, 2025). "Multiple ECM genes are also upregulated in the upper-bulge compartment, including Aspn, Crispld1, Egfl6, and the deafness-related ECM genes Col4a3 and Col4a4." (PMID 30355452, 2018).